ABAT (4-aminobutyrate aminotransferase)
Diseases named in the same sentence as ABAT in open-access papers (continued):
Sharing a sentence is not in itself a finding about the gene and the disease.
bipolar disorder (1 paper, 2020). A disorder of the brain that causes unusual shifts in mood, energy, activity levels and the ability to carry out day-to-day tasks. "Valproic acid was originally developed to treat episodes of bipolar disorder and seizures (nervous system diseases) by hitting the mitochondrial enzymes succinate-semialdehyde dehydrogenase (ALDH5A1) and 4-aminobutyrate aminotransferase (ABAT)." (PMID 32419905, 2020).
Cachexia (1 paper, 2025). Severe weight loss, wasting of muscle, loss of appetite, and general debility related to a chronic disease. "However, preclinical evidence indicates that aBAT activity may contribute to weight loss and cancer cachexia, a condition characterised by profound malnutrition and systemic metabolic disruption." (PMID 39985422, 2025).
cerebellar tumor (1 paper, 2021). "Results showed that ABAT is significantly upregulated in LMD samples relative to the primary cerebellar tumor." (PMID 34192534, 2021).
encephalomyopathies (1 paper, 2022). "Of note, ABAT variants were also responsible for encephalomyopathies with a neurometabolic disorder of GABA degradation resulting in an elevated GABA in the brain as well as mtDNA depletion syndrome highlighting ABAT as an enzyme of dual function." (PMID 35884972, 2022).
GABA-transaminase deficiency (1 paper, 2019). "GABA-transaminase deficiency is a rare neurodevelopmental and neurometabolic disorder caused by mutations in ABAT and resulting in accumulation of GABA in the cerebrospinal fluid (CSF)." (PMID 31133775, 2019). "As succinate also is formed downstream of ABAT activity, and it is involved in mitochondrial physiology, a diagnosis of GABA-transaminase deficiency needs to be differentiated from mitochondrial diseases due to mutations in mitochondrial DNA or other aspects of mitochondrial physiology." (PMID 31133775, 2019). "Global biochemical profiling of EDTA plasma was performed on six samples from four unique subjects with GABA-transaminase deficiency and several subjects without variants in ABAT taking medication that inhibits GABA-transaminase or otherwise may alter GABA metabolism (n = 93)." (PMID 31133775, 2019).
ischemia (1 paper, 2016). A hypoperfusion of the BLOOD through an organ or tissue caused by a PATHOLOGIC CONSTRICTION or obstruction of its BLOOD VESSELS, or an absence of BLOOD CIRCULATION. "Furthermore, accelerating the metabolism of glutamate into succinic acid via GABA shunt enzymes, including 4-aminobutyrate aminotransferase, was neuroprotective against ischemia and reperfusion injury." (PMID 27082425, 2016).
lymph node metastasis (1 paper, 2019). "In this study, we identified 4 coding genes associated with overall survival in LUAD patients with lymph node metastasis, namely, LDHA, ABAT, FAM117A and INPP5J, in the training set." (PMID 31015800, 2019).
mesenchymal tumors (1 paper, 2017). "All three GABA related genes -- glutamate decarboxylase 1 (GAD1) and 2 (GAD2) and 4-aminobutyrate aminotransferase (ABAT) -- were lower in mesenchymal tumors, which in contrast showed higher IDO1 (indoleamine 2, 3-dioxygenase 1) and TDO2 (tryptophan 2, 3-diaxygenase)." (PMID 28245795, 2017).
myocardial disorder (1 paper, 2022). A disorder that affects the muscle tissue of the heart. "A reduction in ABAT in HFD-fed mouse hearts suggests a potential role of ABAT in lipid overload-induced myocardial disorders." (PMID 35216295, 2022).
rhinitis (1 paper, 2021). An inflammation of the mucous membrane lining the nose, usually associated with nasal discharge. "Two enzymes involved in butyrate metabolism, including 4-aminobutyrate aminotransferase and diaminobutyrate-2-oxoglutarate transaminase, were protectively associated with rhinitis (p < 0.01), consistent with the LEfSe analysis." (PMID 34118964, 2021).
Wolfram syndrome (1 paper, 2021). Wolfram syndrome (WS) also known as DIDMOAD, is a neurodegenerative disorder characterized by type I diabetes mellitus (DM), diabetes insipidus (DI), sensorineural deafness (D), bilateral optical atrophy (OA) and neurological signs. "Examples include CISD2, a causal gene for Wolfram syndrome which manifests with early-onset diabetes and ABAT, which encodes Gamma-aminobutyric acid transaminase (GABA-T)." (PMID 34456865, 2021).
tumor (22 papers, 2016 to 2025). "Collectively, these results suggest that loss of ABAT promotes brain metastasis and tumor growth in NSCLC by increasing GABA levels." (PMID 39972344, 2025). "The enrichment of MET pathway genes in tumors with upregulated ABAT transcripts indicates a decreased likelihood of invasive cells exiting the primary tumor, suggesting that low ABAT levels are associated with a predisposition for metastasis." (PMID 33187258, 2020). "Additionally, we discovered that the suppression of tumor malignancy caused by ABAT overexpression could be further enhanced by exogenous GABA to some extent." (PMID 39972344, 2025). "To further confirm these findings, we investigated the role of ABAT in NSCLC in vivo, revealing that high ABAT expression levels reduced the brain metastasis, tumor weight and volume." (PMID 39972344, 2025). "We further analyzed ABAT expression using data from the TCGA, which showed that ABAT levels were lower in tumor tissues compared to adjacent tissues." (PMID 39972344, 2025). "Mechanistically, tumor cells with a tendency for brain metastasis can inhibit 4-aminobutyrate aminotransferase (ABAT) by downregulating forkhead box A2 (FOXA2) expression, leading to increased GABA accumulation." (PMID 39972344, 2025). "Our studies suggest ABAT expression fluctuates depending on metabolite changes in the tumor microenvironment, with nutrient-poor conditions upregulating ABAT expression." (PMID 34192534, 2021). "We then analyzed ABAT expression in the cerebellar and metastatic tumor sites 21 days post-tumor injection, thereby interrogating the initial stages of metastasis formation." (PMID 34192534, 2021). "Based on this evidence, we questioned why a tumor whose identity is intertwined with uncontrollable growth would maintain the capacity to express ABAT, a protein that halts its proliferative capabilities." (PMID 34192534, 2021). "Fluorescent quantitative PCR assays showed that ABAT expression was reduced in 94% of tumor tissues." (PMID 32093682, 2020). "In this latter cohort, those with upregulated ABAT transcripts (n = 5) had a lower likelihood of developing new neoplasms following initial therapy, relative to unaltered (n = 28) (chi-squared test; p = 2.6 × 10−3)." (PMID 33187258, 2020). "In this study, we analyzed blood lipid level in tumor-free healthy Chinese adults in order to determine the role of aBAT in lipid metabolism." (PMID 27566674, 2016). "Furthermore, the loss of ABAT was associated with increased malignancy in NSCLC, whereas its overexpression inhibited tumor progression." (PMID 39972344, 2025). "Previous studies have observed GAD1 upregulation and ABAT downregulation in tumor cells." (PMID 40837580, 2025). "Specifically, we found that tumor cells with brain metastasis tendency could inhibit ABAT by inhibiting FOXA2 expression, thereby reducing the breakdown of GABA and increasing the accumulation of GABA." (PMID 39972344, 2025). "Interestingly, the gene ABAT acts as a tumor suppressor of KIRC, and ABAT_33905_AA expression in KIRC patients is significantly higher than that in normal samples, which deserves further study and exploration." (PMID 36140823, 2022). "Further validation via another database revealed that 4 hub genes, ACAT1, SLC2A2, PCK1 and ABAT, were correlated with tumor survival of HCC in T2DM with HbA1c ≥ 6.5%, suggesting the prognostic prediction function of these 4 genes and even new therapeutic targets in HCC." (PMID 33865459, 2021). "MB is a highly heterogeneous tumor; thus, we investigated whether ABAT is also heterogeneously expressed." (PMID 34192534, 2021). "However, we noticed that although ABAT expression is decreased in MB compared with normal cerebellum, rare ABAT-expressing cells are found among the tumor bulk and less aggressive MB subtypes WNT and SHH express higher ABAT levels." (PMID 34192534, 2021). "Our study identified that loss of ABAT and ALDH6A1 contributes to ccRCC tumor growth." (PMID 32093682, 2020).
tumor (continued). "Favorable clinical attributes such as a living survival status and no new neoplasms following the start of therapy were associated with a lower degree of ABAT methylation (unpaired t-tests)." (PMID 33187258, 2020). "In addition, the aBAT-positive group might represent a subgroup with a distinct hormonal or tumour phenotype leading to an altered catecholamine production or metabolism." (PMID 39985422, 2025). "In contrast, in brain metastases, upregulation of ABAT is frequently observed, facilitating the catabolism of neuron-derived GABA for tumor energy metabolism, suggesting that the function of GABA signaling varies dramatically depending on the tumor context." (PMID 40837580, 2025). "In most peripheral solid tumors, elevated expression of GAD1 and downregulation of GABA-degrading enzyme ABAT in tumor cells lead to the accumulation of GABA in the tumor microenvironment, thereby promoting tumor growth and immune evasion." (PMID 40837580, 2025). "Within the 37-gene-set, we highlight GPM6A (Glycoprotein M6A), ABAT (4-Aminobutyrate Aminotransferase), GFAP (Glial Fibrillary Acidic Protein), and AQP4 (Aquaporin-4), known to play roles in tumor invasion and progression within various cancers." (PMID 40575267, 2025). "Among these, we found some key genes previously reported to be involved in tumor invasion and progression in other types of tumors, such as GPM6A, ABAT, GFAP, and AQP4." (PMID 40575267, 2025). "A previous study indicated that ABAT and aldehyde dehydrogenase 6 family member A1 (ALDH6A1) worked as a tumor suppressor in ccRCC, thereby suppressing tumorigenic capability." (PMID 36176391, 2022). "We show that elevated ABAT expression results in increased GABA catabolism, decreased tumor cell proliferation, and induction of metabolic and histone characteristics mirroring GABAergic neurons." (PMID 34192534, 2021). "Instead, ABAT promotes survival in nutrient-deprived conditions, providing evidence as to why increased expression is found in the LMD compared with the primary tumor." (PMID 34192534, 2021). "Metabolic reprogramming in tumor cells can preclude epigenetic effects and influence cellular differentiation status, indicating that an increase in ABAT expression, and thus a phenotypic change in metabolism, may induce transcriptional and chromatin changes in tumor cells." (PMID 34192534, 2021). "The results still showed decreased expression of ABAT and ALDH6A1 in tumor compared with paraneoplastic tissues (p < 0.0001)." (PMID 32093682, 2020). "We also demonstrated that ABAT and ALDH6A1 are directly regulated by a well-known tumor suppressor, transcription factor HNF4A." (PMID 32093682, 2020). "Several of the understudied genes are directly involved in critical metabolic pathways of tumor etiology, including glucose metabolism (SORD), lipid biosynthesis (FAR1), cAMP signaling pathway (PDE7A, ADCY6), and glutamate anaplerosis (ABAT, GLUD1)." (PMID 31231467, 2019). "Results showed that LMDs have high ABAT and ALDH5A1 expression, indicating that ABAT may serve a vital role for metastatic tumor cells in the CSF." (PMID 34192534, 2021). "Furthermore, the analysis revealed that ABAT expression was not correlated with tumor stage, lymph node metastasis status, or distant metastasis status." (PMID 39972344, 2025). "Notably, GAD1 expression is upregulated in CRC cell lines and tumor tissues, while ABAT expression is downregulated, suggesting the accumulation of GABA in CRC may be attributed to elevated GAD1 and a lack of ABAT." (PMID 37610689, 2024). "In line, our data showed that ABAT is not repressed by methylation, but it is in fact hypomethylated throughout its entire TRR and overexpressed in ACP samples from cluster ACP-B, what could render mitochondrial metabolic advantages for tumor proliferation and disease recurrence in these patients." (PMID 40575267, 2025).
cancer (17 papers, 2012 to 2025). A tumor composed of atypical neoplastic, often pleomorphic cells that invade other tissues. "In primary tumors of other cancers, high ABAT transcript expression is associated with favorable patient outcomes." (PMID 33187258, 2020). "The rs1641025 SNP in ABAT was significantly associated with opioid responsiveness in cancer pain." (PMID 36422103, 2022). "The ABAT gene is closely related to neurological diseases, but it is also associated with cancer." (PMID 34539973, 2021). "Tumors with upregulated ABAT transcript have enriched expression of genes in the gene ontology pathways of “mesenchymal-to-epithelial transition” and “interferon gamma signaling,” two pathways associated with limiting the spread of cancer." (PMID 33187258, 2020). "In particular, upregulation of tumoral ABAT transcripts is correlated both with favorable clinical outcomes and the overexpression of two biological pathways relevant to limiting cancer progression." (PMID 33187258, 2020). "Consistent with this prediction, both human breast-to-brain metastases, and brain metastases of various cancers in xenograft mouse models show elevated ABAT transcript expression relative to primary tumors." (PMID 33187258, 2020). "While the complexities of ABAT methylation remain to be understood, such regulation may impact cancer progression." (PMID 33187258, 2020). "Therefore, the inhibition of GAD67 expression and promotion of ABAT expression may reduce cancer progression." (PMID 37199392, 2023). "We also examined the expression of ABAT and FOXA2 across various cancer types using the TCGA database." (PMID 39972344, 2025). "ABAT and HK2 have been reported to play crucial roles in cancer metabolism, progression, and therapeutic resistance of cancers." (PMID 35615380, 2022). "More importantly, many genes were affected, and the significant up-regulation of ABAT and CLDN6 genes might inhibit the cancer cells proliferation and induce cell apoptosis." (PMID 35659243, 2022). "The CYP2D6*10 SNP is relevant to tramadol pharmacokinetics and opioid dose requirement, while SNPs within UGT2B7 (rs7439366), ABAT (rs1641025), and P2RX7 (rs1718125) have demonstrated some level of potential clinical relevance to cancer pain pharmacogenomics in Asian patients." (PMID 36422103, 2022). "ABAT and ALDH6A1 have similar expression profiles in cancers." (PMID 32093682, 2020). "However, ABAT and FAM117A remain inadequately investigated in cancer-related research." (PMID 31015800, 2019).
neurological disorders (8 papers, 2019 to 2025). "Co-occurrence of AKR7A2_A142T with similarly disruptive mutations in ABAT or SSADH could therefore result in a neurological disorder that would not otherwise occur in an individual harboring only a single disruptive mutation." (PMID 31515488, 2019).
infection (6 papers, 2013 to 2025). The state of being infected such as from the introduction of a foreign agent such as serum, vaccine, antigenic substance or organism. "Infection with Ad-ABAT increased the levels of ABAT protein and activity in cardiomyocytes." (PMID 35216295, 2022).
heart diseases (1 paper, 2022). "Future studies are needed to determine whether ABAT plays similar roles in other heart diseases." (PMID 35216295, 2022). "Thus, ABAT may represent a new therapeutic target for metabolic disorder-related heart diseases." (PMID 35216295, 2022).
metabolic disorder (1 paper, 2022). "This raises such a possibility that maintaining the mtDNA copy number through the mtDNA salvage pathway and subsequently mitochondrial biogenesis, which is compromised in the heart under metabolic disorders, may be a mechanism by which ABAT protects the heart under lipid overload." (PMID 35216295, 2022).
ABAT also shares sentences with these, for which no sentence is quoted: infantile spasms (5 papers); Alzheimer disease (3); depression (3); diabetes (3); insomnia (3); Obesity (3); schizophrenia (3); brain diseases (2); Cognitive impairment (2); Epileptic encephalopathy (2); focal epilepsies (2); Intellectual disability (2); metastasis (2); psychiatric disorder (2); sleep disorder (2); AADC deficiency (1); adrenocortical carcinomas (1); atherosclerosis (1); Choreoathetosis (1); cocaine addiction (1); colon adenocarcinoma (1); coronary heart disease (1); developmental delay (1); diabetic retinopathy (1); dihydropyrimidine dehydrogenase deficiency (1); dry eye (1); Encephalopathy (1); epilepsy syndrome (1); esophageal squamous cell carcinoma (1); folinic acid-responsive seizures (1).
A further 34 diseases each share a sentence with ABAT in 1 paper.